WDR5 (WD repeat domain 5)
Diseases named in the same sentence as WDR5 in open-access papers (continued):
Sharing a sentence is not in itself a finding about the gene and the disease.
breast carcinoma (18 papers, 2015 to 2025). "The results demonstrated overexpression of FOXM1 partly reversed the decrease in breast cancer cells proliferation caused by knockdown of WDR5." (PMID 35524313, 2022). "In this study, we report that WDR5, the core subunit of methyltransferase complex, is an essential gene for breast cancer progression since its inhibition is associated with reduction of tumorigenesis and metastasis." (PMID 31752957, 2019). "WDR5 overexpression has been clinically associated with worse patient outcomes in breast cancer and hepatocellular carcinoma." (PMID 29925347, 2018). "At the transcriptional level, higher WDR5 expression shows consistent association with poorer breast cancer disease-free survival (DFS) across the three tested data sets." (PMID 26355959, 2015). "Summarized statistics of the association between WDR5 gene expression and breast cancer patient survival." (PMID 26355959, 2015). "Our study reveals the prognostic value of WDR5 expression in breast cancer, which is a potential diagnostic marker in clinical practice." (PMID 26355959, 2015). "The association of WDR5 over-expression with 10-year breast cancer specific death is less significant than with DFS using the GSE24450 data." (PMID 26355959, 2015). "Our findings reveal that WDR5 over-expression is associated with poor breast cancer clinical outcome in three gene expression data sets and BreastMark." (PMID 26355959, 2015). "Here, by studying the association between WDR5 expression and breast cancer outcome using three independent data sets, we find that high levels of WDR5 is prognostic of poor breast cancer survival." (PMID 26355959, 2015). "Consistent with the prognostic role of WDR5, we associated its expression with breast cancer progression and aggressiveness, by making use of a panel of cell lines and PDX models of metastatic tumors, the latter representing patients resistant to different lines of therapy." (PMID 31752957, 2019). "We further analyzed human colon cancer (GSE178341) and human breast cancer (GSE176078) scRNA-Seq datasets to validate the correlation between Wdr5 and immune check points, as well as the correlation between Wdr5 and immune-suppressive cytokines." (PMID 39201460, 2024). "Unexpectedly, WDR5 expression exhibits a positive correlation with HLA level in breast-cancer patients, and notable H3K4me3 deposition is observed at the promoter region of HLA-A, -B, and -C." (PMID 39201460, 2024). "An available human breast-cancer scRNA-Seq dataset (GSE176078) was then used to further determine the link between WDR5 and HLA at the single-cell level." (PMID 39201460, 2024). "The analysis indicated that Wdr5 is positively correlated with PD-1, PD-L1, and Spp1 expression in both human colon cancer and human breast cancer in myeloid cells, epithelial cells, and T cells." (PMID 39201460, 2024). "In this study, we performed an in vivo functional screen of epigenetic factors to identify WDR5 as being required for metastatic breast cancer growth." (PMID 36043466, 2022). "We next sought to identify which of WDR5’s multiple molecular function(s) is required for RP gene expression and breast cancer cell growth." (PMID 36043466, 2022). "Certain DEGs were preferentially regulated in LM2, BrM3, or BoM cells, suggesting that WDR5 can regulate genes in a manner that is dependent on the metastatic proclivities of different breast cancer cell subpopulations." (PMID 36043466, 2022). "As aberrant protein translation affects multiple features of malignant cells, targeting WDR5 would be effective in treating both early or late stages of breast cancer." (PMID 36043466, 2022). "To this end, we reduced WDR5 in additional breast cancer lines spanning three established molecular subtypes: TNBC (MDA-MB-453 and HCC1143), estrogen receptor positive (MCF7, T47D, and MDA-MB-361), and HER2+ (UACC893, BT474, and SKBR3)." (PMID 36043466, 2022).
breast carcinoma (continued). "Here, we leveraged the newly designed WDR5 degrader to test its efficacy in WDR5 degradation in breast cancer cells." (PMID 36043466, 2022). "Our results thus suggest that WDR5 degradation is a potential therapeutic strategy to inhibit metastatic progression in breast cancer." (PMID 36043466, 2022). "On the other hand, we also found DEGs (264 down-regulated and 118 up-regulated) that were shared across all lines, indicative of some conserved WDR5 function across metastatic breast cancer cells." (PMID 36043466, 2022). "The surprising observation that WIN binding by WDR5 is dispensable for breast cancer cell growth prompted us to directly test the requirement for the canonical KMT2 complex components in LM2 cells." (PMID 36043466, 2022). "We found that knockdown of WDR5 in breast cancer cells independently impaired their tumorigenic as well as metastatic capabilities." (PMID 36043466, 2022). "Taken together, our data demonstrates that either genetic or pharmacological inhibition of WDR5 can suppress RP gene expression and global translation in breast cancer cells." (PMID 36043466, 2022). "Next, we tested the requirement for WDR5 in other cell line models and from distinct breast cancer subtypes." (PMID 36043466, 2022). "WDR5 inhibition or degradation suppresses translation and growth of breast cancer cells, alone or in combination with mTOR inhibitors." (PMID 36043466, 2022). "Future studies will be needed to elucidate how WDR5-dependent protein translation contributes to the different steps of breast cancer progression, dissemination, and colonization." (PMID 36043466, 2022). "Consistently, pharmacological inhibition or degradation of WDR5 impedes cellular translation rate and the clonogenic ability of breast cancer cells." (PMID 36043466, 2022). "Here, we established an in vivo screening platform that identified WDR5 as a key regulator of breast cancer cell growth and metastatic colonization." (PMID 36043466, 2022). "In summary, MS67-mediated WDR5 degradation showed improved growth inhibition of breast cancer cells when compared to the OICR-9429 compound." (PMID 36043466, 2022). "Expression analysis showed that the majority of WDR5 targets were overexpressed (z-score ≥ + 2) (n = 1093 breast cancer patients)." (PMID 31752957, 2019). "By employing gene expression profiling upon WDR5 inhibition in breast cancer, we found that WDR5 transcriptionally regulates gene signatures, typically involved either in proliferation and cell cycle, or in metastasis, EMT, and their correlated functions." (PMID 31752957, 2019). "A further important finding of this study is that WDR5 activates TGFβ in breast cancer and that targeting the WDR5-TGFβ axis by a small molecular inhibitor reduces the migratory potential of breast cancer cells." (PMID 31938027, 2019). "Association between WDR5 expression and metastasis-free survival (MFS) in 295 breast cancer patients was calculated using PROGgene V2 software on NKI publicly available data sets." (PMID 31752957, 2019). "Depletion of WDR5 reduced ErbB2 expression and cooperated with trastuzumab or chemotherapy to reduce ErbB2-positive breast cancer cell growth." (PMID 29925347, 2018). "WDR5 associates with Cbx8, maintains histone H3K4 trimethylation at Notch-network gene promoters and is required for Notch signaling activation and breast cancer tumorigenesis." (PMID 30488017, 2018). "BreastMark has been robustly validated and has previously been used independently to link over-expression of the WDR5 gene to poor clinical outcome in breast cancer." (PMID 28558008, 2017). "The importance of WDR5 in breast carcinomas has recently attracted increasing attention, mostly focusing on its cooperations with immunohistochemical markers such as ER and human epidermal growth factor receptor 2 (HER2)." (PMID 26355959, 2015).
breast carcinoma (continued). "In lung cancer and breast carcinoma cells, WDR5 could recruit protein arginine methyltransferase 5 (PRMT5) complexes to target gene promoters, enhancing the deposition of H3K4me3 to promote gene transcription and cancer cell invasion." (PMID 35371306, 2022). "Decreasing WDR5 reduces breast cancer cell growth and lung metastasis." (PMID 36043466, 2022). "WDR5 knockdown significantly reduced the clonogenic outgrowth of all the tested cell lines, suggesting that WDR5 enhances tumor cell growth across multiple breast cancer subtypes." (PMID 36043466, 2022). "WDR5 targeting significantly reduces breast cancer cell growth across breast cancer subtypes." (PMID 36043466, 2022). "WDR5 has also been implicated in the growth of metastatic breast cancer cells, although the mechanism underlying this function of WDR5 is not clearly delineated." (PMID 36043466, 2022). "Furthermore, a combination of WDR5 targeting with mTOR inhibitors leads to potent suppression of translation and proliferation of breast cancer cells." (PMID 36043466, 2022). "WDR5 silencing induced a significant reduction of cell motility with respect to the control (shLuc), quantified as displacement (μm) in the box plots (about 40%) (***: p value < 0.001), suggesting that WDR5 regulates breast cancer cell motility, as previously observed in other systems." (PMID 31752957, 2019). "Here, we provide evidences that the WDR5 inhibitor OICR-9429 is able to sensitize breast cancer cells to chemotherapy by reversing the mesenchymal phenotype, overcoming drug resistance, as similarly reported for other epigenetic inhibitors undergoing clinical trials (i.e., Mocetinostat)." (PMID 31752957, 2019). "We speculated that a similar mechanism is in place in breast cancer and is due to WDR5 regulation, which has a prominent role per se in EMT and metastasis, as well as through TGFβ1." (PMID 31752957, 2019). "Finally, our data support WDR5 inhibition as a novel strategy to reverse mesenchymal features and sensitize cancer cells to chemotherapy, thus restricting tumor metastasis in breast cancer." (PMID 31752957, 2019). "We speculated that WDR5 could induce EMT in breast cancer and that its inhibition could reverse the mesenchymal phenotype, consistent with known plasticity of this cellular program whereby cells switch from the mesenchymal to the epithelial states and back." (PMID 31752957, 2019). "Indeed, WDR5 inhibitor sensitizes cells to paclitaxel, revealing a promising combination to eradicate tumor cells in chemo-resistant breast cancer patients." (PMID 31752957, 2019). "Besides, it is reported that the transactivation of WDR5 activates ER signalling in breast cancer cells, and the WDR5-PHB2 complex has a crucial role in the modulation of ER signalling in breast cancer cells." (PMID 26355959, 2015). "Our study reveals the prognostic value of WDR5 expression in breast cancer which is under long-range regulation of genes involved in cell cycle, and anthracycline could be coupled with treatments targeting WDR5 once such a regimen is available." (PMID 26355959, 2015). "Also, we propose WDR5 as a potential drug target for breast cancer treatment which is combinable with traditional regimen such as anthracycline." (PMID 26355959, 2015). "In this study, we are interested in understanding the potential prognostic value and the regulatory mechanism of WDR5 expression for breast cancer survival, particularly for patients receiving the anthracycline regimen (a chemotherapy commonly used in breast cancer)." (PMID 26355959, 2015). "The scRNA Seq dataset analysis also confirmed the positive correlation between Wdr5 and PD-1, PD-L1, and Spp1, as well as the positive correlation between Wdr5 and both TGFβ and IL6 in both human colon cancer and human breast cancer." (PMID 39201460, 2024).
breast carcinoma (continued). "A similar phenomenon can be observed in correlation between Wdr5 and both TGFβ and IL6 in both human colon cancer and human breast cancer in myeloid cells, cancer epithelial cells, and T cells." (PMID 39201460, 2024). "We used MBC2 and MBC26 PDXs to test the effect of WDR5 inhibition on lethality in combination with paclitaxel (PTX), indicated for first-line therapy in TN breast cancer and later-line therapy in ER+ metastatic breast cancer." (PMID 31752957, 2019). "In conclusion, we have demonstrated that WDR5 couples EMT and metastatic progression in breast cancer." (PMID 31752957, 2019). "Then, we suggest WDR5 inhibition as a therapeutic strategy to hit the EMT network, reduce metastasis, and sensitize breast cancer cells to chemotherapy." (PMID 31752957, 2019). "Specific targets of KMT2/MLL epigenetic regulation have been shown to include hTERT (KMT2A, in melanoma), several HOX genes (KMT2A), ERalpha target genes in breast cancer (KMT2D), and androgen receptor target genes in prostate cancer (MLL1 and WDR5)." (PMID 29925347, 2018). "In lung squamous cell carcinoma and breast carcinoma cells, protein arginine methyltransferase 5 (PRMT5) complexes with MEP50/WDR77, and WDR5 is recruited by the protein complex to target gene promoters, resulting in histone H3K4 trimethylation, target gene transcription and cancer cell invasion." (PMID 30488017, 2018). "However, the relative importance of different WDR5 effector functions and their requirement for breast cancer progression and metastasis have not been well studied." (PMID 36043466, 2022). "WD repeat domain 5 (WDR5), a core subunit of the histone methyltransferase (HMT) complex positively correlated with a higher clinical stage and histological grade of tumor, is methylated by SET6 at K207 and K325 in breast cancer cells to promote cell proliferation and migration." (PMID 35216622, 2022). "WDR5 binds c-Myc and N-Myc proteins via their MYC box IIIb motif, and the interaction is essential for histone H3K4 trimethylation at Myc-responsive element E-Boxes of Myc target gene promotes, Myc target gene transcription and Myc-induced cancers, such as breast cancer and neuroblastoma." (PMID 30488017, 2018).
colorectal cancer (17 papers, 2017 to 2025). A primary or metastatic malignant neoplasm that affects the colon or rectum. "Previous data have shown that ALKBH4 functions to suppress colorectal cancer metastasis through competitive binding to WDR5." (PMID 37207134, 2022). "LncRNA SATB2-AS1 enhances the transcription of SATB2 by binding to growth arrest and DNA damage-inducible protein GADD45 alpha (GADD45A) and WD repeat-containing protein 5 (WDR5), which in turn inhibits the metastasis of colorectal cancer." (PMID 34830378, 2021). "The importance of WDR5 in colorectal cancer is suggested by its selective upregulation in colon tumor cells and tissues compared to normal colonic epithelium." (PMID 29925347, 2018). "Consistent with our results, experiments in colorectal cancer showed that WDR5 expression could be increased through activating PI3K/AKT signaling." (PMID 36016936, 2022). "Taken together, this study uncovers that DDX21 interacted with WDR5 to promote colorectal cancer cell proliferation by activating CDK1 expression, suggesting that targeting DDX21 may be an alternative new strategy for CRC treatment." (PMID 35371306, 2022). "The SATB2-AS1 recruits WDR5 and GADD45A to the SATB2 promoter and catalyzes DNA demethylation and histone 3 lysine 4 trimethylation to prohibit colorectal cancer cells’ progression." (PMID 40961095, 2025). "SATB2-AS1 is the cognate antisense transcript of SATB2, and SATB2-AS1 activates SATB2 in cis by recruiting WDR5 and GADD45A to the SATB2 promoter region and inhibits the progression of colorectal cancer." (PMID 36056355, 2022). "This study found that SATB2-AS1 interacted with chromatin regulatory proteins WDR5 and GADD45A in colorectal cancer cell species, with WDR5 catalyzing Lys4 trimethylation and affecting transcription when bound to methylated H3K4." (PMID 34660577, 2021). "HOTTIP could maintain the stemness of cancer stem cells (PCSCs) through the HOTTIP/WDR5/HOXA9/Wnt axis in pancreatic cancer; lncRNA H19 mediated the methotrexate resistance in colorectal cancer through activating Wnt/β-catenin signaling." (PMID 34690755, 2021).
pancreatic cancer (17 papers, 2015 to 2025). "Nevertheless, WDR5 expression exhibits a positive correlation with HLA level in human cancer cells, and H3K4me3 enrichment is found at the promoter regions of the HLA-A, HLA-B, and HLA-C genes in pancreatic cancer cells based on an Encode database analysis." (PMID 39201460, 2024). "The expression of the OPN proteins was mainly regulated by the WDR5–H3K4me3 epigenetic axis, and the inhibition of WDR5 significantly improved the effect of anti-PD-1 immunotherapy in inhibiting pancreatic cancer growth in vivo." (PMID 38303018, 2024). "For the mouse pancreatic tumor model in vivo, the inhibition of Wdr5 significantly repressed pancreatic tumor growth in tumor weight and effectively downregulated the H3K4me3 level in total tumor tissues." (PMID 39201460, 2024). "To verify WDR5 expression in human pancreatic cancer patients, we analyzed WDR5 expression in five pairs of human pancreatic tumor tissues and adjacent normal pancreas." (PMID 39201460, 2024). "An analysis of the dataset revealed that WDR5 exhibits higher RNA level in pancreatic tumor tissues than in adjacent normal pancreas." (PMID 39201460, 2024). "Nevertheless, in this research, we determined that the WDR5/MLL1-H3K4me3 epigenetic axis regulates pancreatic tumor tumorigenicity and immune suppression in the tumor microenvironment." (PMID 39201460, 2024). "Both the IHC and PCR analyses showed that WDR5 exhibits a significantly higher expression in human pancreatic tumor tissues compared with adjacent normal pancreas." (PMID 39201460, 2024). "In this study, we first demonstrated that WDR5 is present at a higher level in human pancreatic tumor tissues compared with adjacent normal pancreases." (PMID 39201460, 2024). "We report here that WDR5 has a higher expression level in human pancreatic tumor tissues, and WDR5 expression is negatively correlated with cancer patients’ response to chemotherapy/immunotherapy in human colon cancer and melanoma." (PMID 39201460, 2024). "Using mouse tumor cell lines and in vivo tumor models, we determined that WDR5 deficiency or inhibition significantly represses MHC I expression in vitro and in vivo in pancreatic tumor cells." (PMID 39201460, 2024). "We report here that WDR5 exhibits a higher expression level in human pancreatic tumor tissues compared with adjacent normal pancreas." (PMID 39201460, 2024). "A comparison with KPC cells revealed that only RUVBL1, RUVBL2, TRRAP, SPT6 and WDR5 were essential in pancreatic tumours and more important for KPC cells than fibroblasts (Δlog2FC<0)." (PMID 38821858, 2024). "This group provided strong evidence for WDR5 as being essential for pancreatic tumorigenesis and thus targeting it as a potential therapeutic strategy to further explore for pancreatic cancer patients." (PMID 30986992, 2019). "The overexpression of WDR5 is not unique to colon cancer as recent studies have demonstrated WDR5 is overexpressed in several cancer types including breast, prostate, bladder, and pancreatic cancer." (PMID 29925347, 2018). "Two available WDR5 inhibitors with low efficacy, OICR-9429 and MM-401, show that WDR5 inhibition slowed proliferation in pancreatic cancer." (PMID 28505071, 2017). "Strikingly, WDR5-47 therapy dramatically suppressed pancreatic tumor growth in vivo." (PMID 39201460, 2024). "In our previous study, we determined that OPN is a novel immune checkpoint which compensates for PD-L1 function to support tumor immune escape in the pancreatic tumor microenvironment, and the WDR5/MLL1-H3K4me3 epigenetic axis regulates both PD-L1 and OPN expression." (PMID 39201460, 2024).